CRP (C-reactive protein)
Diseases named in the same sentence as CRP in open-access papers (continued):
Sharing a sentence is not in itself a finding about the gene and the disease.
irritable bowel syndrome (24 papers, 2010 to 2025). Irritable bowel syndrome (IBS) is a chronic functional condition of the lower gastrointestinal (GI) tract characterized by abdominal pain or discomfort and disordered bowel habit (diarrhea, constipation, or fluctuation between the two). "At inclusion, high s-zonulin values were associated with a high waist-hip-ratio, irritable bowel syndrome and diarrhoea, and with high values of HbA1c, p-glucose, CRP, gamma-GT and the dysbiosis index." (PMID 32698783, 2020). "In the present study, the CRP cut-off value of <0.05 mg/dL for predicting patients with normal colonic mucosa such as irritable bowel syndrome roughly corresponded to this previous result." (PMID 38792498, 2024). "A comprehensive meta-analysis that evaluated serological markers in 2145 subjects identified as having IBD or irritable bowel syndrome plus healthy controls revealed that a CRP value of ≤0.5 mg/dL predicted a ≤1% probability of IBD with good accuracy." (PMID 38792498, 2024). "The sensitivity of CRP ranges from 70 to 100% in the differential diagnosis between CD versus irritable bowel syndrome and ranges from 50 to 60% in UC." (PMID 33971899, 2021). "CRP has also been used to differentiate functional bowel disorders such as irritable bowel syndrome from CD." (PMID 34513858, 2021). "Plasma and sera from 3 patients suffering from either enteric dysmotility, irritable bowel syndrome (IBS) or gastroparesis were analysed for C-reactive protein (CRP), and for GnRH antibodies and soluble CD40 by ELISA methods." (PMID 20487533, 2010). "The measurement of a patient’s CRP value is the serological test most commonly used to exclude IBD in patients with irritable bowel syndrome." (PMID 38792498, 2024). "CRP and hemoglobin are helpful insofar as they are reflective of the clinical response to infliximab induction and can help differentiate common concurrent diagnoses such as irritable bowel syndrome or chronic pain syndrome, which may obscure clinical response." (PMID 38398240, 2024). "Petkov and colleagues, in the patients with irritable bowel syndrome, also showed anti-inflammatory effects of PMA zeolite through lowered levels of the highly sensitive C-Reactive Protein." (PMID 38893490, 2024). "Laboratory markers supporting IBD diagnosis include inflammatory markers such as C-reactive protein (CRP) and erythrocyte sedimentation rate (ESR), alongside fecal markers like calprotectin which are useful in differentiating IBD from irritable bowel syndrome (IBS)." (PMID 40565217, 2025). "For example, patients with irritable bowel syndrome (IBS) treated with PMA-ZEO showed lower blood hsCRP (highly sensitive C reactive protein) levels and decreased stool α1-anti-trypsin levels, suggesting that PMA-ZEO might decrease systemic inflammation in humans." (PMID 36425572, 2022). "Personalization of treatment is done testing biomarkers such as calprotectin (Cal), serum C-reactive protein (CRP), fecal lactoferrin (Lf) and polymorphonuclear neutrophil elastase (PMN-e), especially used to differentiate IBD patents from those with irritable bowel syndrome (IBS)." (PMID 32423084, 2020). "Irritable bowel syndrome is diagnosed based on symptoms; serological testing is suggested to exclude celiac disease, but routine testing for C-reactive protein (CRP), fecal calprotectin or food allergies is not recommended." (PMID 31294724, 2019).
knee osteoarthritis (24 papers, 2014 to 2026). "Our nominally significant finding that CRP might be a potential causal factor for knee osteoarthritis (using GRSGWAS) should be interpreted with caution." (PMID 27327646, 2016). "It remains to be further investigated whether weight gain over the lifetime mediates the potential causal association between genetically elevated CRP and knee osteoarthritis." (PMID 27327646, 2016). "Among 596 women with hip and/or knee osteoarthritis, ultra‐sensitive CRP level intensity correlated with pain." (PMID 39222043, 2024). "The results of the study suggest that bioavailable turmeric extract is as effective as paracetamol in reducing pain and other symptoms of knee osteoarthritis and found to be safe and more effective in reducing CRP and TNF-α." (PMID 33516238, 2021). "In patients with knee osteoarthritis, the consumption of A. lappa root tea for 42 days decreased the levels of serum IL-6, CRP, and MDA." (PMID 31771282, 2019). "In line with our findings, we have previously shown that levels of CRP were higher in women with early radiological knee osteoarthritis (i.e., Kellgren-Lawrence grade 2+) and in women whose disease progressed." (PMID 27327646, 2016). "The aim of this study was to examine the associations of elevated serum C-reactive protein (CRP) and erythrocyte sedimentation rate (ESR) with change in muscle strength in patients with established knee osteoarthritis (OA), at 2 years." (PMID 24928303, 2014). "In addition, Singhal’s study suggests that bioavailable turmeric extract is as effective as paracetamol in reducing pain and other symptoms of knee osteoarthritis, and is safe and more effective in reducing C-reactive Protein (CRP) and TNF-α." (PMID 39519204, 2024). "The included studies showed improvements in the IBR (cytokines, adipokines, and C-reactive protein) in individuals with different clinical conditions (healthy elderly, obese subjects, healthy males, and elderly knee osteoarthritis patients) using several WBV protocols." (PMID 36429572, 2022). "The roles of C-reactive protein (CRP) and cartilage oligomeric matrix protein (COMP) in knee osteoarthritis (KOA) remain controversial, thus the present study is aimed to explore the relationships between CRP, COMP, and the incidence/progression of KOA." (PMID 29351749, 2018). "Leptin tends to increase the levels of C-reactive protein (CRP) and may have a role in maintaining neuropathic pain and pain related to knee osteoarthritis." (PMID 28226002, 2017).
Mycoplasma pneumoniae pneumonia (24 papers, 2016 to 2026). Interstitial pneumonia caused by extensive infection of the lungs (lung) and bronchi, particularly the lower lobes of the lungs, by mycoplasma pneumoniae in humans. "Studies have shown that clinically relevant risk factors for refractory Mycoplasma pneumoniae pneumonia are extrapulmonary complications, large area lung morphogenesis, and elevated C-reactive protein (CRP) and lactate dehydrogenase (LDH) levels." (PMID 36937948, 2023). "CRP levels were assessed in children diagnosed with Mycoplasma pneumoniae pneumonia (MPP) and A549 lung epithelial cells infected with MP." (PMID 39932324, 2025). "Previous studies had shown that CRP, LDH levels, and fever times are related risk factors for Mycoplasma pneumoniae pneumonia complicated with plastic bronchitis." (PMID 35770160, 2022). "Previous studies have shown that refractory Mycoplasma pneumoniae pneumonia (RMPP) is associated with prolonged fever, high levels of C-reactive protein (CRP), airway hypersecretion and consolidation on chest imaging." (PMID 32847534, 2020). "Patients with mycoplasmal pneumonia had significantly higher CRP, IL-8, IL-10, and IL-18 levels than control subjects." (PMID 26751073, 2016). "Patients with Mycoplasma pneumoniae (MP) infections have markedly higher C-reactive protein (CRP)." (PMID 39932324, 2025). "Likewise, if there was a suspicion of atypical pneumonia (e.g., Mycoplasma pneumonia), partly based on the information on low CRP levels, the chest imaging should probably have shown a new consolidation confirming the suspicion." (PMID 37508261, 2023). "Indexes of blood coagulation and C-reactive protein (CRP) have been reported different between healthy people and mycoplasma pneumoniae pneumonia (MPP) patients, but this difference in MPP patients with different chest imaging findings has rarely been reported." (PMID 33545964, 2021). "Although the tests for herpes simplex virus and the mycoplasma pneumonia IgM antibodies were positive, her PCT and CRP levels were significantly increased." (PMID 34425760, 2021). "In children with mycoplasma pneumoniae pneumonia, after treatment with LHQW, the CD3+, CD4+, and CD8+ T cell subsets in patients were significantly altered, and IL-6, c-reactive protein (CRP) in serum and procalcitonin (PCT) levels significantly reduced." (PMID 32483409, 2020). "Comparison of inflammatory markers and white blood cell counts among children with Mycoplasma pneumoniae pneumonia, with and without coinfections (hs-CRP highest in MPP + H." (PMID 41367602, 2025). "Fever ≥10 days, CRP ≥137 mg/L, and consolidation >2/3 pulmonary lobe may predict the occurrence of sequela in MPP (Predictive factors for sequela of bronchitis obliterans in refractory mycoplasma pneumoniae pneumonia, to be published in Zhonghua Er Ke Za Zhi)." (PMID 37082710, 2023).
Thromboembolism (24 papers, 2013 to 2025). The formation of a blood clot inside a blood vessel that subsequently travels through the blood stream from the site where it formed to another location in the body, generally leading to vascular occlusion at the distant site. "We also found that extended periods of high CRP levels were associated with lower risks for major bleeding and thromboembolism or major thromboembolism alone." (PMID 40909455, 2025). "In contrast, CRP level >60 mg/dL for ≥72 h was associated with lower risk for major bleeding and thromboembolism (OR: 0.2; CI 0.07–0.5; p = 0.002), and major thromboembolism (OR: 0.2; CI 0.1–0.5; p < 0.001) compared to reference CRP ≤ 60 mg/dL for ≥72 h or >60 mg/dL for <72 h." (PMID 40909455, 2025). "The link with CRP has been previously reported and may explain greater risk of thromboembolism in OC users." (PMID 28234958, 2017). "First, there are multiple factors, including inflammation, infection, thromboembolism, cardiovascular disease and tissue damage, that may affect CRP levels." (PMID 38297200, 2024). "CRP and ferritin are the markers of inflammation, while D-dimers can be used to distinguish patients who may develop severe forms of the disease and thromboembolism." (PMID 35742601, 2022). "In patients with thromboembolic disease the hs-CRP level, LDH level, and ESR were usually normal." (PMID 24391746, 2013). "C-reactive protein (CRP) plays an important role in the processes of thrombogenesis and thromboembolism." (PMID 31396017, 2019). "CRP = C-reactive protein; LDH = lactate dehydrogenase; PT= prothrombin time; ICU = intensive care unit; IMPROVE = International Medical Prevention Registry on Venous Thromboembolism." (PMID 35936165, 2022).
vascular dementia (24 papers, 2004 to 2025). A degenerative vascular disorder affecting the brain. "Subgroup analysis revealed that higher CRP levels were correlated with deterioration in visuospatial ability and a notably greater risk of conversion to vascular dementia (OR/HR = 2.769, p = 0.000)." (PMID 41373439, 2025). "A longitudinal cohort demonstrated that systemic inflammation levels measured by fibrinogen and C-reactive protein (CRP) were associated with an increased risk of vascular dementia." (PMID 39777309, 2024). "Specifically, Gorelick and colleagues suggested that high levels of CRP and IL-6 resulted in nearly a 3-fold increase in vascular dementia risk." (PMID 23308123, 2013). "Moreover, a MR study using data from the FinnGen cohort demonstrated higher CRP to be associated with an increased risk of vascular dementia." (PMID 37178386, 2023). "Finally, in contrast to VVV-BP and ABPV, LF-BPV was negatively associated with the odds of having elevated CRP and with levels of IL-6, consistent with protection against AD and vascular dementia." (PMID 37693005, 2023). "There are also markers of inflammation, such as C-reactive protein levels (CRP) and interleukin-6 (IL-6) that are elevated in the blood plasma of patients with AD and vascular dementia." (PMID 30096929, 2018). "The Honolulu Asia Aging Study (HAAS) found that raised levels of C-reactive protein (CRP; an inflammatory marker) in mid-life was associated with a significantly increased risk for vascular dementia (VaD) and AD, with or without the presence of cardiovascular disease (CVD)." (PMID 23008797, 2012). "Another RCT of 42 patients with vascular dementia and Fazekas scores of ≥ 2 found a trend towards reduction in WMH volume and inflammatory markers (CRP, IL-6 and tumour necrosis factor-alpha; TNFα) in the RIC group at 6 months follow-up." (PMID 39702489, 2024). "Consequently, localized increases in CRP may be associated with vascular dementia but not detected with serum measurements." (PMID 15476562, 2004).
alcohol abuse (23 papers, 2011 to 2025). The use of alcoholic beverages to excess, either on individual occasions ("binge drinking") or as a regular practice. "These include low serum albumin (<30 g/L), C-reactive protein >100 mg/L, platelet count >400 × 109/L, serum sodium <130 mmol/L, IV drug use, and chronic alcohol abuse." (PMID 40519425, 2025). "Higher pre-treatment CRP (HR = 3.53; 95% CI: 1.50–8.32; p = 0.004), higher lymph node status (HR = 3.28; 95% CI: 1.33–8.12; p = 0.010), and alcohol abuse (HR = 5.78; 95% CI: 1.04–31.97; p = 0.045) were independent adverse prognostic factors for DFS." (PMID 35565464, 2022). "The CRP level significantly correlated with age, alcohol abuse, pre-treatment NLR (neutrophil/lymphocyte ratio), PLR (platelet/lymphocyte ratio), tumor stage, and nodal involvement (all p < 0.05)." (PMID 32182693, 2020). "Recent data suggests that for individuals who meet criteria for alcohol abuse (based on the Michigan Alcohol Screening Test), black individuals demonstrate higher urine norepinephrine, serum C-reactive protein, and serum interleukin-6 levels compared to white individuals." (PMID 31568479, 2019). "In patients from whom blood cultures were taken, alcohol abuse was the only factor associated with culture positivity, as CRP level was not." (PMID 31011854, 2019). "Although factors such as infection, acute and chronic inflammation, and alcohol abuse can exert an influence on individual values, both the stable clinical condition and the concomitant low CRP in all patients suggest that the serum ferritin mainly reflected body iron stores." (PMID 21687645, 2011). "In addition, alcohol abusers had higher values of CRP, NLR, and MLR than the other people." (PMID 38349459, 2024).
autism (23 papers, 2009 to 2025). Persistent deficits in social interaction and communication and interaction as well as a markedly restricted repertoire of activity and interest as well as repetitive patterns of behavior. "This is in line with studies showing high levels of CRP in autism, which has been associated with poor cognitive empathy." (PMID 30955108, 2019). "A clinical study with 1.2 million pregnancies showed that the risk of autism in the children of women with the highest levels of C-reactive protein, a well-known marker of inflammation, was 43 % higher than women with the lowest levels." (PMID 27184741, 2016). "Increasing maternal CRP levels were significantly associated with autism in offspring." (PMID 32859040, 2020). "A large Finnish cohort study (n = 1.2 million) revealed that maternal C-reactive protein (CRP) was associated with increased risk of autism in children, although a significant interaction between maternal CRP and sex could not be demonstrated." (PMID 31071949, 2019). "The objective of this study was to further examine whether maternal mid-pregnancy CRP levels are associated with increased risk of autism and other developmental delays and whether this association might be influenced by genetic determinants of CRP levels." (PMID 27093065, 2016). "Analysis of early gestational CRP levels in maternal sera and childhood autism in the Finish birth cohort (consisting of 1.2 million births from 1987–2007) revealed that increased maternal CRP levels were significantly associated with autism in the offspring (OR = 1.12)." (PMID 27458336, 2016). "Yin, Wang combined several smaller clinical studies examining CRP levels, measured around age four, and autism and concluded that autistic children have higher levels of CRP." (PMID 41018677, 2025). "For example, in a large Finnish cohort (n = 1.2 million) there was a significant association between the level of maternal early gestational C-reactive protein (CRP, an inflammatory marker in blood) and autism in the offspring." (PMID 28744200, 2017). "At 1.3 atm, hyperbaric treatment decreased a marker of inflammation (C-reactive protein) in one study of children with autism." (PMID 19284641, 2009). "We previously reported that CRP displayed a u-shaped association with odds of autism in a case-control design, but the association was not significant when comparing siblings." (PMID 41018677, 2025). "The main aims of this study were to assess the changes over time of lipid profile, CRP level and BMI in individuals diagnosed with autism and healthy controls and to assess the factors that may affect these variations, mainly type of diet." (PMID 32859040, 2020). "This is in line with Mendelian Randomization studies observing no causal role of CRP in autism." (PMID 41018677, 2025). "Notably, both IL-6 and CRP levels are elevated in the plasma in the individuals with autism." (PMID 31733650, 2019). "In one study, significant improvements were observed in children with autism with the use of hyperbaric treatment at both 1.5 atm/100% oxygen and 1.3 atm/24% oxygen; neither hyperbaric protocol worsened markers of oxidative stress and both reduced C-reactive protein (a marker of inflammation)." (PMID 19284641, 2009). "Searches on database; Pubmed, Medline, Embase and google scholar using key words; C reactive protein (CRP), Maternal CRP, ASD, autism, autistic disorder, Inflammation." (PMID 32448119, 2020). "CRP was reported to be elevated in blood of patients with GBM, various types of cancers and other pathological conditions, for example autism." (PMID 29513714, 2018). "In the Californian Early Markers for Autism (EMA) case-control study, the third and fourth quartiles of CRP (at 15–19 weeks of gestation) compared to the lowest quartile were associated with a decreased risk of ASD, which is in general agreement with our current findings." (PMID 35393396, 2022).